SEMA7A (semaphorin 7A (JohnMiltonHagen blood group))
Diseases named in the same sentence as SEMA7A in open-access papers (continued):
Sharing a sentence is not in itself a finding about the gene and the disease.
tumor (continued). "Using SEMA7A knockout mice, we are determining the effects of tumor-derived vs. host-derived SEMA7A." (PMID 24550834, 2014). "Gene silencing of SEMA7A in peritoneal elicited macrophages from DA-3 tumor-bearing mice resulted in decreased CXCL2/MIP-2 expression." (PMID 24550834, 2014). "Recently, SEMA7A has been reported to be one of the proteins secreted by glioblastoma tumor cells that contribute to the highly invasive phenotype." (PMID 24550834, 2014). "Together, these results indicate that FAO may be essential for SEMA7A induced M2 polarization in the TME of tumor-bearing mice." (PMID 41019072, 2025). "In addition, glycosylated SEMA7A is involved in regulating cell-extracellular matrix interactions and promoting tumor growth and metastasis." (PMID 40373023, 2025). "Considering that macrophages can express the SEMA7A receptor, the function and polarization status of TAMs in the TME of NSCLC might be affected by the tumor-derived soluble factor SEMA7A." (PMID 41019072, 2025). "Additionally, SEMA7A promotes tumor-related angiogenesis, lymphangiogenesis, dendrite formation, and extracellular matrix remodeling, thereby altering the tumor microenvironment." (PMID 39744480, 2025). "In terms of the underlying mechanisms, the altered polarization status of macrophages in the tumor microenvironment of NSCLC may be responsible for SEMA7A-accelerated tumor progression." (PMID 41019072, 2025). "Since the expression of SEMA7A was most significantly elevated in LUAD cells and has been observed to be closely linked to drug resistance and tumor metastasis in a variety of cancers, it was selected as a representative gene for subsequent functional validation experiments." (PMID 40936767, 2025). "Moreover, knockdown of SEMA7A in LLC cells resulted in a diminished tumor growth characterized by reduced tumor weight and tumor volume, as well as prolonged survival of the tumor-bearing mice." (PMID 41019072, 2025). "Therefore, the observed associations between the expressions of the SEMA7A, SEMA4D, ADAM8, and ADAMTS10 in tumor groups with KRAS, NRAS, BRAF, PIK3CA, and AKT mutations require validation in larger study cohorts." (PMID 39329961, 2024). "SEMA7A belongs to the Semaphorin family and is involved in the oncogenesis and tumor progression." (PMID 38548747, 2024). "Semaphorin 7A (SEMA7A) is a GPI-linked semaphorin that can be released from cell membranes into interstitial fluid and has been reported to have pro-tumourigenic effects in BC, influencing tumour progression, lymphangiogenesis and drug resistance." (PMID 37685898, 2023). "Strikingly, Sema7A blockade impairs substantial anti-tumor response mediated by CIML NK cells." (PMID 35155237, 2022). "In addition, SEMA7A regulates the proliferation, migration, invasion, lymph formation and angiogenesis of multiple types of tumor cells." (PMID 35955933, 2022). "Therefore, Sema7A plays an anti-tumor effect in terms of DCs, but promotes tumor cells migration in the whole TME." (PMID 35155237, 2022). "Due to its chemotactic effects, Sema7A could attract TAMs which could then regulate angiogenesis in the tumor microenvironment." (PMID 32210960, 2020). "Also, we have shown that increased SEMA7A protein expression promotes tumor growth, motility, invasion, and lymphangiogenesis." (PMID 33088913, 2020). "The preceding data may help to further explain the role of collagen, COX-2, and SEMA7A in facilitating tumor progression following lactation." (PMID 30847405, 2019). "The ability to differentially regulate tumor progression could, therefore, be explained by binding of SEMA7A to its different receptors." (PMID 30847405, 2019). "It is also possible that although we have knocked down the gene in the tumor cells, host derived SEMA7A may contribute toward angiogenesis." (PMID 24550834, 2014). "Whether impairment of SEMA7A N-glycosylation blocks tumor progression is also a pivotal issue." (PMID 38548747, 2024).
tumor (continued). "In vivo, SEMA7A knockdown in MCF10DCIS cells led to significant decreases in tumour growth, the lower expression of invasive markers such as p63 and vimentin and the increased expression of E-cadherin, which suggest that the knockdown of SEMA7A may reverse EMT." (PMID 37685898, 2023). "Notably, previous reports showed that Sema7A is partly shed from the cell surface into the tumor microenvironment and can be detected in the blood, which could enable a convenient assessment of its level by liquid biopsies." (PMID 33537086, 2021). "Since tumor cells are known to hijack normal developmental programs, we postulated that sustained expression of SEMA7A in MECs, particularly in postpartum women, could result in pro-tumor characteristics that are similar to those induced by Ras—a known oncogene." (PMID 34561423, 2021). "It is possible that ADAM-17 in the tumor bearers could affect cleavage of SEMA7A." (PMID 24550834, 2014). "Semaphorin 7A (SEMA7A), a soluble tumor-derived molecule, can modulate the proliferation, invasion and angiogenesis of multiple types of cancers." (PMID 41019072, 2025). "Regulation of this miRNA occurs through the lncRNA LOXL1-AS1, which sponges miR-28-5p, leading to increased expression of semaphorin 7A (SEMA7A) and inducing tumor progression." (PMID 40563399, 2025). "The results showed that the expression levels of SEMA7A were significantly elevated in LUAD and LUSC tumor tissues compared with normal tissues." (PMID 41019072, 2025). "This suggests that SEMA7A protein levels determined by IHC can potentially be used as a biomarker to identify specific subgroups of ACC patients and score tumor aggressiveness instead of or in conjunction with RNA-Seq analyses." (PMID 40647379, 2025). "Transcriptome analysis showed upregulation of brain‐derived neurotrophic factor (BDNF), semaphorin 7A (SEMA7A), and plexin‐B2 (PLXNB2) in SUDHL6‐EBV derived tumor tissues." (PMID 40488319, 2025). "Through RNA-Seq analysis of HNSCC samples (3 tumors and 3 para-carcinoma tissues), we identified 8 pivotal marker genes (PCDH7, CDH2, ITGA3, SEMA7A, TMEM132A, CD276, TMEM2, GPR158) that were overexpressed in tumor specimens." (PMID 38548747, 2024). "Tumor cells were cotransfected with si-RBM4/RBM4-OE and SEMA7A-WT/5NQ and were then subjected to a CCK8 assay." (PMID 38548747, 2024). "Previous studies have shown that semaphorin 7a (SEMA7A), as upstream regulator of CHI3L1, stimulates macrophage/TAM integration into lymphatic vessels to facilitate lymphatic entry and spreading of tumor cells." (PMID 38605414, 2024). "Thus, in the context of tumor, Sema7A could promote angiogenesis in multiple ways." (PMID 32210960, 2020). "SEMA7A, COX-2, and collagen all represent important effectors of macrophage-mediated tumor cell growth, survival, and metastasis." (PMID 30847405, 2019). "In cancer, fibrillar collagen coordinates upregulation of COX-2 on tumor cells, further promoting tumor cell invasion and metastasis, and we have published that COX-2 drives SEMA7A expression." (PMID 30847405, 2019). "To understand which molecules are responsible for this tumour-supporting function, we performed a descriptive proteomic analysis of GASC-exosomes and identified, among the others, Semaphorin7A (SEMA7A)." (PMID 31151295, 2019). "In our in vitro model, relying on GASC and GSC obtained from the same tumour, the treatment of GSC, both with recombinant SEMA7A-Fc and exosomes produced by GASC, stimulated a rapid FAK phosphorylation and significantly increased the motility of GSC." (PMID 31151295, 2019). "To evaluate SEMA7A expression in the NSCLC, we examined the expression of SEMA7A in human tumor tissues and non-carcinoma adjacent tissues, using the TCGA databases." (PMID 41019072, 2025). "Knockdown of SEMA7A in cancer cells may suppress NSCLC progression, in parallel with a diminished M2 polarization in the tumor microenvironment (TME)." (PMID 41019072, 2025).
tumor (continued). "In the present study, decreased fatty acid oxidation, but not glucose metabolism, was observed in the TAMs sorted from the tumor tissues of SEMA7A-silenced LLC-bearing mice, suggesting fatty acid oxidation may be required for SEMA7A-mediated M2 polarization." (PMID 41019072, 2025). "In addition, SEMA7A is highly expressed across different cancer types (for example, HNSCC), with overexpression in tumor tissues compared to paired para-cancerous samples." (PMID 38548747, 2024). "Considering the paired sample differential analysis, expression correlation analysis, immunological and tumour microenvironment correlation analysis, as well as the line chart results, CEMACAM3, LCK, PARP1, PDGFB, PLK1, SEMA7A and SPHK1, were considered as prognostic genes of higher value." (PMID 39656479, 2024). "The expression of SEMA7A, COX-2, and collagen during postpartum involution and their known roles in facilitating tumor progression suggest these molecules and their interplay may be important drivers of PPBC." (PMID 30847405, 2019). "Although it is known that SEMA7A is expressed by monocytes, activated T cells, and keratinocytes, it is not known if tumor cells express SEMA7A." (PMID 24550834, 2014). "The expression of SEMA7A's receptor, β 1 integrin, in peripheral macrophages between normal and tumor bearers has not yet been well characterized." (PMID 24550834, 2014). "SEMA7A is known to belong to a SEMA7A-integrin-β1 axis that activates Mitogen-Activated Protein Kinase (MAPK) cascades, especially the ERK/MAPK signaling pathway, which plays crucial role in regulating oncogenic functions, including metastasis and tumor progression." (PMID 40647379, 2025). "However, in C3H mice bearing Sema7a -WT-re-expressing SCC7- Sema7a-KO xenograft tumors, the combined treatment with 2F-Fuc and anti-PD-L1 antibodies conspicuously suppressed tumor growth and expansion, as confirmed by the tumor observation and growth curves of the xenograft tumors." (PMID 38548747, 2024). "However, biological effects of SEMA7A glycosylation have rarely been elucidated, nor have the molecular mechanisms that regulate the N-glycosylation of SEMA7A and subsequently affect tumor progression." (PMID 38548747, 2024). "It was not known if SEMA7A is solubilized in our tumor model." (PMID 24550834, 2014). "Interestingly, while SEMA7A is known to affect monocyte activation in vitro via β 1 integrin–mediated effects, the role of SEMA7A in the activation of tumor cells has not yet been studied." (PMID 24550834, 2014). "However, it should be noted that knockdown of SEMA7A did not influence the percentages and absolute numbers of CD4+T, CD8+T and Treg cells in the TME of tumor-bearing mice, suggesting that macrophages might be the main target cells of SEMA7A." (PMID 41019072, 2025).
cancer (29 papers, 2012 to 2026). A tumor composed of atypical neoplastic, often pleomorphic cells that invade other tissues. "SEMA7A, or CD108w, was first recognized for its expression on lymphocytes; however, a role for SEMA7A in cancer was later identified through its association with Plexin-C1, the receptor for the viral homolog of SEMA7A." (PMID 30847405, 2019). "For SEMA3A, SEMA3C, and SEMA7A as well as the semaphorin receptor neuropilin, there was a clear trend where the expression above the cutoff was associated with worse survival for all three cancers." (PMID 37719704, 2023). "Recently, studies have revealed that SEMA7A can act as a key player in the tumorigenesis and metastasis of many types of cancers." (PMID 41019072, 2025). "We have previously established a relationship between SEMA7A signaling through proteinase kinase B (AKT) in cancer cells." (PMID 40470186, 2025). "One of the direct targets of miR-28–5p is Semaphorin 7A (SEMA7A), which promotes the proliferation and migration of cancer cells by regulating integrin-mediated signaling pathways and ERK activation." (PMID 39136001, 2024). "SEMA7A is also one of our selected hub genes that play a key role in several cancers including pancreatic, breast, and lung cancers." (PMID 38092774, 2023). "Our results are the first to identify a role for SEMA7A in anoikis resistance and promotion of stem and cancer cell phenotypes via activation of α6 and β1-integrins." (PMID 34561423, 2021). "In neurons, Sema7A-PlexinC1 signalling regulates synapse development and neuroglial plasticity, while, in cancer, PlexinC1 is involved in cell migration and proliferation." (PMID 31151295, 2019). "Prior work revealed that Semaphorin-7a (SEMA7A) also promotes cancer stem cell and pro-survival phenotypes in luminal progenitor cells during involution, and we observe a population of luminal progenitor cells that co-expresses Sox9 and Sema7a during involution." (PMID 42239249, 2026). "Additionally, SEMA7A regulates the proliferation, migration, invasion, lymphatic vessel formation, and angiogenesis of various types of cancer cells and controls the inflammatory functional phenotype of macrophages." (PMID 37958549, 2023). "SEMA7A is known to signal through β1-integrin in immune cells, neurons, and cancer; β1-integrin also mediates MEC survival during development, in part, via phosphorylation and activation of downstream pro-survival signaling mediated by PI3-kinase and protein kinase B, or Akt1." (PMID 34561423, 2021). "Interestingly, SEMA7A‐positive fibroblasts were located only in the restricted area that was close to the cancer cells." (PMID 32931156, 2020). "Abnormal SEMA7A expression during involution and/or cancer may promote tumorigenesis via activation of β1-integrin and downstream pathways." (PMID 30847405, 2019). "Although cancer cells typically express abnormal levels of SEMAs, the role of SEMA7A in cancer progression is largely unknown." (PMID 26378920, 2015). "Therefore, SEMA7A plays pivotal roles in tumoral progression and metastasis of several types of cancers." (PMID 26378920, 2015). "Although many classes of semaphorins have been studied in different cancers, the role of sempahorin7A (SEMA7A) in cancer progression is largely unknown." (PMID 24550834, 2014). "In this study, based on the comprehensive prognostic analysis of the blood group antigen genes in pan-cancers, we found that the high expression of SEMA7A in KIRC was associated with poor prognosis of KIRC patients, implying that SEMA7A may be a novel unfavorable prognostic biomarker for KIRC." (PMID 35955933, 2022). "Thus, the role of SEMA7A in luminal B cancers should be explored." (PMID 33088913, 2020). "Thus, fibrillar collagen, COX-2, and SEMA7A may be a part of a feed-forward loop that ultimately results in cancer cell invasion and metastasis." (PMID 30847405, 2019). "Sema3E, Sema4D, and Sema7A were shown to contribute to EMT, whereas Sema3B, Sema3F, and Sema5A inhibited EMT in cancer cells." (PMID 35775491, 2022).
cancer (continued). "Among them, ephrin receptor EPHA4, actin binding LIM-proteins ABLIM1 and ABLIM2, semaphorin SEMA7A and glial neurotrophic factor GFRA2 genes, which are involved in axon guidance, are commonly repressed in cancer cells by DiPRO1 and SIX1." (PMID 39009887, 2024). "Unlike Plexin-C1, SEMA7A-mediated activation of β1-integrin has been shown to promote cancer progression." (PMID 30847405, 2019). "The results of the cancer-related pathway analysis showed that the high expression of these antigen genes was mainly related to the activation of the epithelial–mesenchymal transition (EMT) pathway, whereby CR1 and SEMA7A were involved in up to 41% of cancer types." (PMID 35955933, 2022). "SEMA7A was first identified for its expression on lymphocytes, but has since been shown to exert diverse roles in neuronal development, cell differentiation, ECM deposition, various components of the immune system, and pathologies including fibrosis and cancer." (PMID 34561423, 2021). "Of note, cancer cells were also positive for LIF, SEMA7A, and HAS1, while they were negative for αSMA." (PMID 32931156, 2020).
cardiovascular diseases (3 papers, 2019 to 2025). "Semaphorin 7A (Sema7A) has been reported to regulate endothelial phenotypes associated with cardiovascular diseases in KD." (PMID 39857904, 2025). "Semaphorin 7A (Sema7A) has been reported to regulate endothelial phenotypes associated with cardiovascular diseases, while its role in KD remains unknown." (PMID 38678170, 2024).
SEMA7A also shares sentences with these, for which no sentence is quoted: endothelial dysfunction (3 papers); infectious disease (3); malaria (3); neurodegenerative disease (3); Neurological Disorders (3); head and neck squamous cell carcinoma (2); idiopathic pulmonary fibrosis (2); systemic sclerosis (2); viral myocarditis (2); acute kidney injury (1); acute lung injury (1); Adrenocortical Carcinoma (1); airway allergy (1); alcohol dependence (1); allergic conjunctivitis (1); amyloid (1); astrocytoma (1); benign tumor (1); brain diseases (1); cerebral atherosclerosis (1); clear cell renal cell carcinoma (1); diabetes (1); ductal carcinoma in situ (1); familial intrahepatic cholestasis (1); gout (1); Heat Stroke (1); hepatocellular carcinoma (1); Huntington disease (1); immune diseases (1); infection (1).
A further 27 diseases each share a sentence with SEMA7A in 1 paper.